BRAF (B-Raf proto-oncogene, serine/threonine kinase)
Diseases named in the same sentence as BRAF in open-access papers (continued):
Sharing a sentence is not in itself a finding about the gene and the disease.
melanoma (continued). "However, the strong association between BRAF V600E and CIMP that emerges in colorectal cancer is not observed in melanoma." (PMID 34944843, 2021). "However, the combination of the pan-class 1 P13K inhibitor BKM120 with vemurafenib in both BRAF inhibitor-naïve and -resistant patients with advanced melanoma was poorly tolerated and did not warrant further study." (PMID 34680615, 2021). "For traditional chemotherapies, BRAF inhibitors such as vemurafenib (PLX4032) and encorafenib, or MEK inhibitors such as cobimetinib, trametinib, and binimeinib, have been used for the treatment of melanomas mainly by inhibiting cell proliferation by blocking downstream ERK1/2 activity." (PMID 34103468, 2021). "miR-31 host gene (MIR31HG) lncRNA is upregulated in OIS upon BRAF overexpression, binds directly to SUZ12 polycomb repressive complex 2 subunit and EZH2, thus is required for the repression of the INK4A locus, whereas knockdown of MIR31HG promotes a p16INK4A-dependent senescence of melanoma cells." (PMID 34638331, 2021). "In cells resistant to combined BRAF and MEK inhibition, PAKs modulate the phosphorylation of JNK and β-catenin and the activation of the mTOR pathway, supporting that PAK signaling is responsible for acquired resistance to MAPK inhibitors in BRAF-mutant melanoma." (PMID 34804979, 2021). "However, many characteristics of melanoma remain elusive and do not explain why only a small subset of patients respond to BRAF and/or MEK inhibitors and only for a limited duration (6–9 months)." (PMID 33613844, 2021). "However, it appears that block of Olig2 and BRAF&MEK inhibition do not show a distinct synergistic effect in reducing the viability of melanoma cells." (PMID 33833342, 2021). "Additionally, BRAFV600E melanoma cells have increased senescence characteristics with increased SA-β-gal activity and expression of SASP factors, including IL-8 and TGFβ, compared to wild type BRAF melanoma cells." (PMID 34066966, 2021). "However, although MEK inhibitors are effective against BRAF-mutant melanoma and in neurofibromatosis, they have shown only modest or no response in clinical trials in RAS-mutant tumours." (PMID 34200676, 2021). "BRAF mutant melanoma patients that never received treatment had a median OS of only 6.6 months." (PMID 34677256, 2021). "In addition, the inhibition of ERK phosphorylation significantly enhanced apoptosis in BRAF- and NRAS-mutant melanoma spheroids, but not the wild-type BRAF/NRAS spheroid model." (PMID 33804655, 2021). "Similar observations were reported for freshly isolated melanoma cells, independent of whether patients were sensitive or resistant to BRAF inhibitors." (PMID 33498201, 2021). "Besides, research has showed that a combination of anti-PD-1/PD-L1 antibody and CTLA-4 inhibitor can improve treatment effects of patients with advanced melanoma, which was approved by the FDA in treating BRAF V600 E wild-type patients with unresectable or metastatic melanoma." (PMID 34876903, 2021). "Unfortunately, responses were not durable in a significant number of cases: after 18 months of treatment with vemurafenib, only approximately 14% of patients experienced durable drug response and no relapse, as melanoma cells developed resistance to BRAF inhibition." (PMID 34831420, 2021). "Specifically, lung cancer patients with MET exon 14 skipping are responsive to MET inhibitors despite not having other activating alterations, while melanoma patients expressing a BRAF isoform lacking exons 4–8, which encodes for the RAS binding domain, exhibit resistance to BRAF inhibitors." (PMID 33482911, 2021). "Therefore, the combination of vemurafenib and IFN-α in patients with BRAFV600E melanoma may provide therapeutic benefits; MEK inhibition may prevent the reactivation of the MAPK pathway induced by BRAF inhibitor resistance." (PMID 33407577, 2021).
melanoma (continued). "Unlike in melanoma, where BRAF mutation status could help to identify responders to vemurafenib, other mechanisms of response must be at play in HNSCC as BRAF mutations are uncommon in HNSCC51." (PMID 34907286, 2021). "The drug was effective in melanoma cells regardless of whether the cells were sensitive or resistant to BRAF inhibitors, whereas no toxicity was observed in normal cells." (PMID 33498201, 2021). "These diverse mechanisms of action of cannabinoids may serve as a potential therapy in case of triple negative melanomas (harboring wild-type BRAF, NRAS and PTEN), which do not respond to a novel immunotherapy." (PMID 34264513, 2021). "Moreover, the demonstration that co-targeting BRAF/MEK and PI3K enhances the anti-tumor efficacy of PD1 blockade in melanoma indicates that BRAF and PI3K co-inhibition acts not only through direct induction of tumor cell death, but also indirectly by enhancing anti-tumor immunity." (PMID 34439194, 2021). "Thus, ipilimumab clearly adds to the beneficial effect of anti-PD-1 therapy in patients with BRAF-mutant melanoma; however, it is not a part of current triplet combination regimens." (PMID 33827575, 2021). "Furthermore, we observed a negative correlation of DUSP6 and SPRY4, two negative feedback regulators of MAPK signaling with the presence of CD8+ T-cells in pre-, but not in on-treatment BRAF-mutant melanoma patients (left)." (PMID 34535668, 2021). "Indeed, effects on tumoral volume and tumoral growth both in xenograft-sensitive and resistant to BRAF inhibitor mice models show that CRO15 is able to induce melanoma cell death without apparent toxicity in mice." (PMID 33431809, 2021). "To investigate whether CDK4/6 inhibition alone or in combination with BRAF and MEK inhibition alters metabolic pathways in melanoma, we utilised the BRAF mutant melanoma cell lines WM266.4 and A375 and specific inhibitors of CDK4/6 (palbociclib), BRAF (vemurafenib), and MEK (cobimetinib)." (PMID 33572972, 2021). "Metastatic melanoma is managed with a combination of immunotherapy (CTLA-4 checkpoint inhibitor ipilimumab and PD-1 inhibitors nivolumab and pembrolizumab), targeted therapy (BRAF inhibitors vemurafenib, dabrafenib, and encorafenib), and chemotherapy (dacarbazine and temozolomide)." (PMID 34071176, 2021). "There is also not clear consensus on whether concurrent BRAF inhibition with SRS increases the risk of radionecrosis in melanoma brain metastases." (PMID 33992087, 2021). "Indeed, BRAF and MEK inhibitors have been shown to increase melanoma-cell radiosensitivity." (PMID 33804655, 2021). "However, unlike BRAF mutant melanoma, no targeted therapy has yet been approved for NRAS mutant melanoma so far." (PMID 33732653, 2021). "Therefore, BRAF-targeted therapy, based on the inhibition of the mitogen‐activated protein kinase (MAPK) pathway, has spurred a revolution in the treatment of advanced melanoma." (PMID 37304648, 2021). "The coupling of inhibitors against BRAF/MEK, BRAF/JNK, MEK/Plk1, MEK/pan-RAF, and PI3K/MAPK have been explored as promising approaches; however, these strategies only uncover a fraction of the therapeutic potential contained in combinatory treatment of melanoma." (PMID 33807778, 2021). "Given the potential for NRAS/BRAF/PI3K mutant melanoma to be particularly sensitive to RGS, it is important to evaluate whether RGS is effective in preclinical models for the treatment of melanoma." (PMID 34092233, 2021). "However, activation of BRAF or NRAS is insufficient to promote melanoma initiation without senescence bypass mediated by additional founder mutations or expression changes of several genes including p16INK4A, CTNNB1, PTEN, or MDM43–7." (PMID 34140478, 2021). "Although it could not be verified after subcloning due to the lack of informative BRAF SNPs, this finding is consistent with what is already described in melanoma." (PMID 34208446, 2021).
melanoma (continued). "This suggests that ABCB5 may not be a useful therapeutic target for patients with BRAF inhibitor-resistant melanoma." (PMID 35048028, 2021). "The knowledge that the biology is more complex and heterogeneous in CRC than in melanoma is supported by several preclinical data suggesting that, differently from melanoma, CRC cell lines express high levels of activated EGFR, which convey a reactivation of MAPK pathway following BRAF inhibition." (PMID 34299337, 2021). "However, we showed that combining MEKi with TRT induces a marked increase in apoptosis of BRAF- and NRAS-mutant melanoma cells, which could be specific to TRT irradiation or related to the spheroid 3D architecture." (PMID 33804655, 2021). "Thus, a simple EZH2 inhibitor is not a suitable alternative for solid tumor, such as the BRAF inhibitor resistance melanoma treatment." (PMID 33849069, 2021). "The trials of the BRAF/MEK inhibitors were limited to patients with BRAFV600E and BRAFV600K mutations and who showed an ORR between 60 and70%, which indicated that 30–40% of BRAF mutant melanoma patients did not respond to the targeted therapy." (PMID 34831002, 2021). "Of note, the activation of P300 also contributes to the resistance to BRAF-targeted therapy by activating ERK signal and mitochondrial oxidative phosphorylation, highlighting targeting P300 as a valuable synergistic therapeutic approach to sensitize melanoma cells toward MAPK pathway inhibition." (PMID 34924562, 2021). "In addition, in the presence or absence of BRN2, melanoma cells are either more resistant or more sensitive to BRAF inhibitors, respectively." (PMID 34140478, 2021). "In recent years, BRAF/MEK inhibitor combinations including dabrafenib/trametinib, vemurafenib/cometinib, and encorafenib/binimetinib have been approved by the FDA, leading to median progression-free survival (PFS) of up to 14.9 months in BRAF mutant melanoma patients." (PMID 33921974, 2021). "RNF43-overexpressing melanoma cells do not develop resistance to BRAF V600E targeted therapies." (PMID 34702444, 2021). "In addition, the combined treatment with BRAF and PDK1 inhibitors prevents melanoma growth." (PMID 33446631, 2021). "The use of CRISPRa screening in BRAF (V600E) melanoma cells for resistance to the BRAF inhibitor PLX-4720 not only reproduced previously known resistance mechanisms, such as EGFR and ERK pathway activation but also revealed novel resistance mechanisms regarding G protein-coupled receptors." (PMID 34598686, 2021). "The clinical implementation of BRAF and MEK (mitogen-activated protein kinase kinase) inhibitor therapies has resulted in dramatic improvements in OS and progression-free survival (PFS) rates in patients with BRAF(+) advanced melanoma cases over the last few years." (PMID 32605090, 2020). "We analyzed a few of the top DEGs (NRP2, CAPN3, DMBT1, BRAF, DDIT3, PPP1R3C, NF1) using The UCSC Xena platform that has large number of RNA-seq data of normal tissue from healthy individuals (GTEx) and primary tumor and metastatic tissue data from melanoma patients (TCGA)." (PMID 32983966, 2020). "In melanoma cells, ARAF or CRAF may be overexpressed, while BRAF is blocked." (PMID 32605090, 2020). "Confirmatory molecular investigations for specific neoplasms are important for the use of targeted therapies such as BRAF or CDK4 inhibitors (in confirming that patients have melanoma rather than CCS and for patients with DDL, respectively) and for patient enrolment into appropriate clinical trials." (PMID 33061792, 2020). "Overall, the clinical response data for the trametinib plus durvalumab combination arms in BRAF-wild type melanoma could not clearly demonstrate whether doublet therapy improved the response rate in comparison with historical controls." (PMID 33288749, 2020).
melanoma (continued). "Importantly, the incidence of congenital neurological disease, and apparently of melanoma, was not altered by genotype; no cases of melanoma were seen in BRAF‐mutant multiple CMN, however, this genotype is rare." (PMID 31111470, 2020). "For instance, targeted therapies (such as BRAF inhibitors and MEK inhibitors) have been shown to potentiate immune checkpoint inhibitor activity in preclinical models, but when used together in melanoma patients severe irAEs were observed forcing closure of the study." (PMID 32849557, 2020). "This is especially true for patients who show no benefit after standard of care, become resistant or belong to somatic mutation subgroups for which no targeted therapy option exists, such as BRAF wild-type melanomas including NRAS mutant and NF1 loss-of-function melanomas." (PMID 33260923, 2020). "Interestingly, patients with heterogeneous acral melanomas had worse survival than those with BRAF-negative melanomas (p = 0.0065, log-rank test)." (PMID 32143442, 2020). "We observed that Gal-1 is basally expressed in parental drug-sensitive melanoma cells, but its silencing had no significant impact on their viability in the absence of BRAF inhibitors, suggesting that in this condition Gal-1 autocrine signaling is either disabled or irrelevant for growth." (PMID 32784465, 2020). "Before immune checkpoint inhibitors (ICIs), BRAF inhibitors and MEK inhibitors became available in the real world, DTIC, type I IFN and/or IL-2-based combined therapies were the main protocol for the treatment of advanced melanoma, although the efficacy of those protocols remained insufficient." (PMID 32948031, 2020). "In a previous work, with the aim to verify whether Ole might potentiate drug efficiency on BRAF mutant melanoma cells, we decided to use a non-toxic 250 μM dose able to reduce cell proliferation rate without affecting cancer cell viability and apoptosis." (PMID 32013090, 2020). "Although the peptidomimetic NRP1 inhibitor EG00229 could rescue responsiveness to BRAF-targeted therapy in resistant melanoma cells, drug resensitization was never complete." (PMID 32784465, 2020). "These cells simultaneously became more resistant to the BRAF inhibitor vemurafenib and the MEK inhibitor cobimetinib, suggesting that the modulation of the DUSP6/ERK5 signaling pathway by MIR211 is related to the development of BRAF/MEK inhibitor resistant melanoma." (PMID 33628737, 2020). "Moreover, BRAF-mutated melanoma cell cultures enriched in CSCs showed an overexpression of SCD1 and were more resistant to BRAF and MEK inhibitors than non-enriched cultures." (PMID 33202944, 2020). "However, targeting BRAF is an effective treatment in melanoma, but not for colorectal cancers containing the same mutation." (PMID 32069833, 2020). "Had such an assumption been made, BRAF inhibitors would not have been developed for melanoma." (PMID 32066498, 2020). "Therapeutic options for patients with advanced-stage melanoma have been increased in the last years, and approval of new therapeutic agents such as the checkpoint inhibitors (anti-CTLA4 and anti-PD1 antibodies) and BRAF/MEK inhibitors has opened new expectations for survival." (PMID 32486190, 2020). "However, the results of the IMspire 170 phase III trial comparing atezolizumab + cobimetinib to pembrolizumab in 450 patients with untreated BRAF WT melanoma proved negative." (PMID 32585901, 2020).
melanoma (continued). "Moreover, we showed that melanoma cells consume more oxygen after inhibition of BRAF, thus suggesting that the effect was not due to reduced oxygen consumption by melanoma cells either." (PMID 31833658, 2020). "We then evaluated 34 antitumor agents across eight melanoma PDXCs, compared drug response to BRAF and MEK inhibitors alone or in combination with PDXC and the corresponding PDX, and investigated novel drug combinations targeting BRAF inhibitor-resistant melanoma." (PMID 31857724, 2020). "Detectable ctDNA before complete surgical resection in patients with AJCC stage IIIB/C/D (high-risk stage III) with a BRAF, NRAS, or KIT mutant melanoma is an independent predictor of worse melanoma-specific survival (MSS) in patients receiving no systemic adjuvant therapy." (PMID 33233603, 2020). "Enhanced pathway reactivation in CRC relative to melanoma might be suggested as accounting in part for the differences clinically, however combined BRAF/MEK blockade is also highly effective in BRAF mutant lung cancer, a disease which like CRC is characteristically an EGFR expressing cancer." (PMID 32922659, 2020). "In addition, there is no approved targeted therapy for certain subgroups, namely BRAF wild-type melanomas, although they often bear aggressive tumor biology." (PMID 33260923, 2020). "However, by itself oncogenic BRAF is not sufficient for melanoma and must cooperate with other processes to induce the fully cancerous state." (PMID 33212834, 2020). "It has been speculated that inhibition of MCL-1 through miR-32 may represent an efficient therapy for melanoma, regardless of its mutational status (NRAS, BRAF or PTEN), as it was discovered to exhibit synergistic effects with vemurafenib." (PMID 33203119, 2020). "A minority of BRAF V600E melanoma patients (3–5%) have no response." (PMID 32393282, 2020). "The drug is a pan-inhibitor of BRAF, however, sorafenib was not effective in treating melanoma." (PMID 32213878, 2020). "However, there are still no effective targeted therapies for the treatment of melanomas that harbor the wild-type BRAF gene." (PMID 33378376, 2020). "Although our data indicate that Gal-1 and NRP1/EGFR upregulation is a frequent adaptive mechanism in melanoma cells treated with BRAF inhibitors, this signaling cascade may not be critical in every case of melanoma developing drug resistance." (PMID 32784465, 2020). "No BRAF‐mutant patients had been diagnosed with melanoma, but this could be due to the small numbers rather than a genuinely differential genotypic effect." (PMID 31111470, 2020). "However, some studies showed BRAF and NRAS mutations in the same tumor samples, suggesting that these mutations are not mutually exclusive in melanoma but exhibit intra-tumoral heterogeneity." (PMID 32695793, 2020). "Moreover, the Western blot results demonstrated that knocking down the expression of AURKB markedly suppressed activation of the BRAF/MEK/ERKs and PI3-K/AKT pathways in both vemurafenib-sensitive (A375 and M249) and vemurafenib-resistant melanoma cell lines (A375R and M249R)." (PMID 32863956, 2020). "This includes those with BRAF-WT melanoma, and those who do not respond to immunotherapies." (PMID 32764384, 2020). "Inhibition of mutant BRAF (V600E) activity by either the BRAF inhibitor Vemurafenib (PLX4032) or BRAF siRNA markedly reduced the LNK transcript levels in melanoma A375 cells, while forced expression of an activated BRAF (V600E) generated the opposite effect (~four-fold increased LNK)." (PMID 31110180, 2019). "BRAF inhibitors are not as effective as melanoma because of different resistance mechanisms." (PMID 31661924, 2019). "Actinomycin D suppressed the upregulation of TRPM1 mRNA, which is transcriptionally activated upon treatment of melanoma cells with BRAF inhibitor 37 but did not affect HIF1A mRNA, confirming that the dose of actinomycin used was sufficient to block transcription completely." (PMID 31727958, 2019).